FGFRL1 (fibroblast growth factor receptor like 1)
Diseases named in the same sentence as FGFRL1 in open-access papers (continued):
Sharing a sentence is not in itself a finding about the gene and the disease.
cancer (21 papers, 2010 to 2026). A tumor composed of atypical neoplastic, often pleomorphic cells that invade other tissues. "The expression level, the influence on cancer cell’s biological behaviors of FGFRL1, and its roles in cancer progression, chemoresistance, and prognosis." (PMID 40699684, 2025). "In NSCLC, lncRNA FGD5‐AS1 indirectly upregulates FGFRL1 levels and promotes cancer cell proliferation through sponging hsa‐miR‐107305." (PMID 37750089, 2023). "In esophageal squamous cell carcinoma, miR‐210 directly targets FGFRL1 to induce cell death and cell cycle arrest in G1/G0 and G2/M, thereby inhibiting cancer cell survival and proliferation." (PMID 37750089, 2023). "The IHC scores were used to quantify and compare FGFRL1 staining across the entire panel of luminal epithelial and cancer cells." (PMID 35053442, 2022). "In contrast to FGFR1–4, the role of FGFRL1 in cancer research remains underexplored." (PMID 41514604, 2025). "In pairwise analyses of AdjPr and PCa from the same patients in TMA I, membrane-associated staining was significantly weaker in PCa, while IHC scores for cytoplasmic and nuclear FGFRL1 staining were significantly higher in cancer tissues compared to AdjPr (respectively)." (PMID 35053442, 2022). "In addition, exosomal miR-210-3p derived by cancer stem cells targets fibroblast growth factor receptor-like 1 to elicit a pro-metastatic phenotype." (PMID 35928879, 2022). "In order to identify whether gene amplification contributes to higher FGFRL1 expression in OC, our analysis of cancer genomics in TCGA revealed that gene amplification was infrequent in FGFRL1 gene and only 21 of 301 samples (6.75%)." (PMID 29675438, 2018). "miR-210 is a hypoxia inducible gene which may inhibit cancer cell survival and proliferation through targeting FGFRL1." (PMID 22703336, 2012). "Moreover, the study indicated that miR-210-3p may contribute to cancer cell metastasis via the inhibition of FGFRL1." (PMID 34440422, 2021). "miR-210 can attenuate cancer cell activity through downregulating E2F3, fibroblast growth factor receptor-like 1, homeobox protein Hox-A1, homeobox protein Hox-A9 and Max-binding protein." (PMID 33673181, 2021). "Although FGFRL1 lacks the kinase domain, there is some evidence indicating the role of FGFRL1 in the regulation of FGF signaling pathways and cancer progression." (PMID 34830951, 2021). "Fibroblast growth factor receptor‐like 1 (FGFRL1), a member of the FGFR family, has been demonstrated to play important roles in various cancers." (PMID 31957179, 2020). "FGFRL1 can promote ENO1 expression and activate the PI3K/Akt signaling pathway that regulates cell division, differentiation, and apoptosis, and it is one of the most frequently altered signaling pathways in cancer." (PMID 40699684, 2025). "There is compelling evidence for the nuclear localization and functioning of other FGFRs in FGFR-related cancers and congenital diseases, but the nuclear localization of FGFRL1 and its potential functional consequences have not been previously identified." (PMID 35053442, 2022). "Researches in cancer tissues and cells have proved miR-210 could inhibit cell proliferation via a fibroblast growth factor receptor (FGFR)-like 1 (FGFRL1) dependent mechanism since FGFRL1 promotes cell proliferation by facilitating cell cycle progression." (PMID 24586608, 2014).
FGFRL1 also shares sentences with these, for which no sentence is quoted: migraine (2 papers); cardiovascular disease (1); colorectal tumors (1); craniosynostosis (1); disc degeneration (1); glioma (1); heart defects (1); Insulin resistance (1); oral squamous cell carcinoma (1); paraganglioma (1); paroxysmal nonkinesigenic dyskinesia (1); pheochromocytoma (1); renal agenesis (1); seizures disorders (1); serous borderline ovarian tumors (1); serous ovarian carcinomas (1); skeletal dysplasia (1); type 2 diabetes (1).